DLGAP2 (DLG associated protein 2)
Description:
May play a role in the molecular organization of synapses and neuronal cell signaling. Could be an adapter protein linking ion channel to the subsynaptic cytoskeleton. May induce enrichment of PSD-95/SAP90 at the plasma membrane.
Synonyms: DAP-2; SAPAP2; C8orf68; DAP2; ERICH1-AS1
Tractability: Antibody: its Gene Ontology location is reachable by antibodies, with high confidence; UniProt places it where antibodies can reach, with medium confidence.
Gene: Protein-coding gene on chromosome 8 (737,628 to 1,708,476, forward strand). Ensembl gene ENSG00000198010.
Subcellular location: Cell membrane; Postsynaptic density; Synapse
Pathways (Reactome):
Neuronal System: Neurexins and neuroligins
Gene Ontology:
Molecular function: protein binding; molecular adaptor activity
Biological process: modulation of chemical synaptic transmission; neuron-neuron synaptic transmission; signaling
Cellular component: glutamatergic synapse; neurofilament; plasma membrane; postsynaptic specialization; postsynaptic density; synapse
Genetic constraint (gnomAD): Loss-of-function variants: 24 observed, 79.5 expected, observed/expected ratio (o/e) 0.3, 90% interval 0.22 to 0.43. The synonymous counts are far from expectation, so gnomAD's model fits this gene poorly and the ratio says little. Missense variants: 1,843 observed, 1,366.5 expected, observed/expected ratio (o/e) 1.35, 90% interval 1.3 to 1.4. Synonymous variants: 877 observed, 600.7 expected, observed/expected ratio (o/e) 1.46, 90% interval 1.38 to 1.54.
Gene-disease validity (ClinGen):
ClinGen rates the evidence that DLGAP2 causes each of these diseases.
complex neurodevelopmental disorder (autosomal dominant): Limited. A disorder that involves more than one phenotype associated with the central nervous system, including but not limited to intellectual disability, autism, and seizures (epilepsy).
Homologues: Orthologues: macaque DLGAP2 (98% identical), rat Dlgap2 (90% identical), pig DLGAP2 (90% identical), mouse Dlgap2 (90% identical), guinea pig DLGAP2 (89% identical), dog DLGAP2 (83% identical), tropical clawed frog dlgap2 (78% identical), rabbit DLGAP2 (78% identical), zebrafish dlgap2a (70% identical), chimpanzee DLGAP2 (46% identical), zebrafish dlgap2b (35% identical), zebrafish DLGAP2 (34% identical). Paralogues in human: DLGAP1 (48% identical), DLGAP3 (44% identical), DLGAP4 (41% identical), DLGAP5 (14% identical).